S100B (S100 calcium binding protein B)
Diseases named in the same sentence as S100B in open-access papers (continued):
Sharing a sentence is not in itself a finding about the gene and the disease.
depression (continued). "A lack of differences, or lower S100B in first-episode depression patients compared to recurrent depressive episode was reported." (PMID 37759935, 2023). "A positive correlation of S100B concentrations with HDRS scores in the inpatients with depressive episodes, and lack of correlation after treatment, was also reported." (PMID 37759935, 2023). "The present study aimed to investigate whether the BDNF, VEGF, S100B, and IGF-1 in serum levels can be helpful to identify MDD in knee OA patients and to evaluate the potential relationship of these neurotrophins with depression and pain assessments." (PMID 36386998, 2022). "In our study S100B levels were not significantly related to the severity of depression or hypo/manic symptoms, measured using HAMD-17 or YMRS scales, respectively." (PMID 34099858, 2021). "The S100B levels were not related to the severity of depression (HAMD scores) (p = 0.53) or hypo/manic (YMRS scores) (p = 0.34) symptoms." (PMID 34099858, 2021). "Further, we found that this association was specific to anhedonia as there was no treatment arm by S100B interaction for overall depression severity." (PMID 31861074, 2019). "Lastly, we did not assess the S100B and inflammatory markers concentrations in the patients with other severe mental illness, such as major depressive disorder and bipolar disorders." (PMID 27279465, 2016). "Taken together, our finding of increased S100B expression and mRNA levels in the hippocampus of The CUMS model of depression suggests that that S100B overexpression may be a significant marker related to the pathophysiology of the depression." (PMID 27931233, 2016). "Instead, our findings suggest that S100B predicts treatment response independent of depression severity." (PMID 26364276, 2015). "This study is the first to demonstrate that S100B/RAGE interactions may be involved in the development and maintenance of depression and that it may play an important role in the mechanism of antidepressants’ therapeutic action." (PMID 21614209, 2010). "Given the complex nature of depression and the multifactorial aspects of both ω-3 PUFAs and the biomarkers in question, more targeted studies are necessary to explore how ω-3 PUFA supplementation might affect HMGB1, S100β, and NSE levels in individuals with depression." (PMID 39513898, 2024). "Although research on rodent models has shown that antidepressants might reverse an increased level of S100B, studies on human subjects with depression were not as coherent." (PMID 35448545, 2022). "Hamilton Depression Rating Scale, core, sleep, activity, somatic anxiety, and delusion subscale scores were significantly and positively correlated with CSF HGF level, while sleep subscale score was positively correlated with CSF S100B and VEGF receptor 2 levels in patients with MDD (p < 0.05)." (PMID 32439851, 2020). "Besides neurons, also other cell populations are able to secrete S100B: Moutsatsou and colleagues, for example, showed that leukocytes secrete S100B in bipolar disorders, whereas the role of S100B for unipolar depression has not been clarified yet." (PMID 29545905, 2018). "Moreover, changes of S100B in leukocytes have been shown only in bipolar disorder, whereas for unipolar depression, which is more relevant for our data, no studies are available in the literature so far." (PMID 26500502, 2015). "However, S100B levels did not change significantly over time or in response to treatment, regardless of remission status, suggesting that it is not a state marker of depression." (PMID 41440970, 2025). "However, serum S100B, which might not reflect local concentrations in the brain, was rather elevated in acute stages of depression and schizophrenia and positively correlated with depressive symptoms and negative symptoms in schizophrenia." (PMID 22916238, 2012).
depression (continued). "In the serum and CSF of patients with major depression, S100B protein has been shown to be increased compared to levels in healthy controls, although other studies did not demonstrate this difference in the CSF of MDD patients." (PMID 27931233, 2016). "In analogy to major depression we hypothesized a decrease of BDNF and an increase of S100B, without changes of NSE in minor depression." (PMID 26500502, 2015). "Increased S100B in males with minor depression, without alterations in BDNF and NSE, supports the glial hypothesis of depression." (PMID 26500502, 2015). "Similarly, presence of the history of major depression did not affect the levels of BDNF, S100B or NSE in the minor depression group (p = 0.10–0.50); neither in comparison with healthy controls (p = 0.13–0.38)." (PMID 26500502, 2015).
delirium (70 papers, 2006 to 2026). A disorder characterized by confusion; inattentiveness; disorientation; illusions; hallucinations; agitation; and in some instances autonomic nervous system overactivity. "Among CNS injury markers, S100β and neurofilament light chain (NfL) demonstrated the most consistent associations with delirium presence and severity, supporting a role for astrocytic and axonal injury in delirium pathogenesis." (PMID 40889075, 2025). "Previous systematic reviews and meta-analyses have predominantly focused on a limited set of inflammatory and neuronal injury-related biomarkers, such as IL-6, CRP, cortisol, and S100β, in relation to delirium risk." (PMID 40889075, 2025). "Blood loss was also correlated with CPAR, S100B, cerebrospinal fluid lactate, and peak delirium severity, aligning with prior research findings." (PMID 39857699, 2025). "In an observational study of 22 patients with septic shock, 10 of whom experienced delirium, an S100B level exceeding 0.15 μg/L was associated with an odds ratio of 18.0 for delirium." (PMID 39201697, 2024). "The S100B is considered as a calcium-binding protein that has involvement in astrocytes with the central nervous system (CNS) and is associated with delirium." (PMID 39700095, 2024). "Our primary goal was to evaluate S100B levels on admission and their association with delirium occurrence in acutely ill older adults." (PMID 36973363, 2023). "A meta-analysis including 28 observational studies found that biomarkers associated with dementia, such as elevated blood-based levels of IL-6, C-reactive protein, S100B, and NfL, were also associated with delirium." (PMID 37550780, 2023). "Our findings add nuance to prior biomarker work showing greater quartiles of CRP, IL-8, and S-100β measured at delirium onset were associated with increased in-hospital mortality." (PMID 37656731, 2023). "Twelve studies investigated the association between S100β serum concentration at hospital admission and delirium during hospitalization." (PMID 37360340, 2023). "Previous investigations in critically patients have observed that plasma Protein C, PAI-1, and S100B are associated with delirium." (PMID 31856187, 2019). "There appear to be higher levels of IL-6 in patients with delirium and an association between S-100B concentrations and duration of delirium." (PMID 29801516, 2018). "The biomarker S100B has been associated with delirium and acute brain dysfunction in previous studies and is considered a validated measure of BBB disruption." (PMID 27119013, 2016). "Previous studies found that there was an association of delirium and an increased level of serum biomarkers such as neuron-specific enolase or s-100β during severe infection." (PMID 26634124, 2015). "We found that IL-8, MCP-1, procalcitonin (PCT), cortisol, and S100-β were significantly associated with delirium in inflamed patients (n = 46)." (PMID 22206727, 2011). "In univariate logistic regression analysis, IL-8, MCP-1, PCT, cortisol, and S100-β were significantly (P <0.05) associated with delirium." (PMID 22206727, 2011). "Elevated levels of S100B have been shown to be associated with delirium in patients after abdominal surgery, after cardiac surgery and in sepsis-associated delirium." (PMID 19473521, 2009). "The possible association between higher levels of S100B during delirium and the higher risk of developing dementia after delirium is an interesting field for future research." (PMID 19473521, 2009). "Next to delirium, type of fracture, pre- or postoperative status and day of blood withdrawal were all associated with S100B levels." (PMID 19473521, 2009). "Further investigations defining the role of S-100β and cortisol as aids in the diagnosis of sepsis-associated delirium are warranted." (PMID 18457586, 2008).
delirium (continued). "• The significant associations between sepsis-associated delirium and elevated S-100β and cortisol suggest that further investigations defining the role of these markers as aids in the diagnosis of sepsis-associated delirium are warranted." (PMID 18457586, 2008). "In our patients, elevated CRP, S-100β, and cortisol were associated with sepsis-associated delirium." (PMID 18457586, 2008). "Further investigations defining the role of S-100β and cortisol in the diagnosis of sepsis-associated delirium are warranted." (PMID 18457586, 2008). "With regard to possible serum markers, we found significant associations with sepsis-associated delirium for both S-100β (P = 0.029) and cortisol (P = 0.011)." (PMID 18457586, 2008). "In addition, elevated levels of IL-8 and S100β protein have been associated with increased mortality in patients with delirium." (PMID 39895101, 2025). "S100B levels were positively associated with postoperative delirium." (PMID 38928583, 2024). "It is unknown whether greater S100β serum concentration could be a result of chronic inflammation, increasing patients' vulnerability to develop delirium, or greater S100β serum concentration might be the cause for increased vulnerability to delirium." (PMID 37360340, 2023). "Additionally, a greater serum concentration of S100β at hospital admission is associated with a greater likelihood to develop delirium during hospitalization." (PMID 37360340, 2023). "We furthermore found that elevated postoperative S100β, IL-6, and IL-1β concentrations are associated with an increased risk of developing delirium, and interventions reducing their perioperative release may decrease the risk for POD." (PMID 37373482, 2023). "Indeed, even though S-100β is thought to be a major potential biomarker associated with delirium in adults, we used NSE for this study as a previous fundamental study clearly showed longer-duration time course changes in S-100β after hypoxia." (PMID 36333387, 2022). "The odds ratio for the risk of developing delirium with an S100B > 0.15 μg/L was 18.0." (PMID 34991675, 2022). "Increases in the levels of α-synuclein and S100β have been reported to be associated with delirium." (PMID 26441522, 2015). "S100β has also been reported to be potentially associated with delirium in humans." (PMID 26441522, 2015). "Clinical investigations have shown that elevations in the levels of α-synuclein and S100β could be associated with postoperative delirium." (PMID 26441522, 2015). "The main objective of the current pilot studies was to determine whether surgery plus anesthesia was able to induce behavioral (e.g., attention) and biochemical/cellular (α-synuclein and S100β) changes associated with delirium." (PMID 26441522, 2015). "Future experiments should attempt to further test the hypothesis that changes in the levels of α-synuclein and S100β might be, at least partially, the underlying mechanisms of postoperative delirium." (PMID 26441522, 2015). "Increase in the S100β levels has been reported to be associated with postoperative delirium." (PMID 26441522, 2015). "Delirium was associated with increased level of S100B which could indicate cerebral damage either due to delirium or leading to delirium." (PMID 19473521, 2009). "This study among elderly patients admitted for hip fracture showed that delirium was associated with increased level of S100B which could indicate cerebral damage either due to delirium or leading to delirium." (PMID 19473521, 2009). "The results of these studies suggested that surgery plus anesthesia could induce behavioral changes (e.g., loss of attention) as well as biochemical/cellular changes (e.g., increase in the levels of α-synuclein and S100β) in mice, which have been reported to be associated with delirium." (PMID 26441522, 2015). "Finally, in view of the diagnostic difficulties, we addressed the question of whether S-100β and basal cortisol are potential markers for sepsis-associated delirium." (PMID 18457586, 2008).
delirium (continued). "Patients with elevated S100β levels tended to experience longer durations of delirium, suggesting a link between glial activation and the persistence of delirium." (PMID 41440533, 2025). "Human studies have shown that plasma biomarkers of BBB disruption, such as S100β, correlate with the incidence of delirium in postoperative patients, with measurements typically obtained 24–48 h after surgery." (PMID 41375722, 2025). "Another study by Jennifer Taylor further demonstrated that elevated perioperative CPAR and S100B levels correlated with delirium severity, while a reduction in S100B levels was predictive of symptom recovery (p < 0.001)." (PMID 39857699, 2025). "Although S100β protein isa sensitive indicator reflecting early nerve damage, it has more predictive valuefor delirium." (PMID 41437743, 2025). "S100β, an astrocytic calcium-binding protein, has been implied in BBB disruption and neuroinflammation, and was positively associated with delirium severity in multiple studies." (PMID 40889075, 2025). "Additional indicators of neuronal injury, such as S100β, APOE, cortisol, and NSE, have been associated with the onset of delirium post-anesthesia and major surgical procedures." (PMID 40092071, 2025). "Patients with postoperative delirium showed an increase in S100B levels on the first postoperative day." (PMID 38928583, 2024). "Among the unique proteins, we focused on the top 13 most investigated proteins (IL-6, CRP, IL-8, S100B, IL-10, TNF-a, IL-1b, Cortisol, MCP-1, GFAP, IGF-1, IL-1ra, and NFL) that are significantly associated with delirium." (PMID 39700095, 2024). "Neuroinflammation activates microglia, which produce local proinflammatory cytokines and reactive oxygen species, and activates astrocytes, resulting in elevated S-100β levels, with the external manifestation of delirium." (PMID 37715189, 2023). "We also aimed to evaluate the association between S100B, NSE, Tau and cytokine panel (IL-1B, IL-4, IL-10, TNF-α and IFN-γ) with delirium." (PMID 36973363, 2023). "Median of S100B at admission in patients who developed delirium was 0.16 and median was 0.16 in patients who didn’t develop delirium (p: 0.69)." (PMID 36973363, 2023). "S100β has been reported as a potential biomarker for delirium, but its particular relationship with POD remains controversial." (PMID 35982410, 2022). "S100B is used to evaluate brain injury severity and predict outcomes from stroke, traumatic brain injury, encephalopathy, and delirium." (PMID 34991675, 2022). "Clinical evidence of BBB disruption serving a pathophysiologic role in delirium is provided in one study that showed elevated serum levels of S100β, the marker of BBB damage in elderly patients with delirium." (PMID 36030220, 2022). "In adult patients undergoing cardiac surgery, high levels of S100β were observed to be correlated with adverse neuropsychological and psychiatric outcomes and to predict the occurrence of postoperative delirium." (PMID 32245513, 2020). "Recent work correlated markers of systemic inflammation and those of astrocyte and glial cell activation (IL-6, IL-8, IL-10, TNF-α, C-reactive protein and S-100β levels) with longer duration of delirium, more severe delirium and higher in-hospital mortality." (PMID 32443606, 2020). "Although older studies have shown an increase of NSE and S100B serum levels and neurocognitive dysfunction in cardiac surgery, research regarding delirium after cardiac surgery still remains an open issue." (PMID 32987655, 2020). "Using S100B as a marker of BBB leakage, we found that patients who developed delirium more likely had BBB leakage as reflected by higher serum S100B levels." (PMID 30086136, 2018). "An early but transient glial response in delirium is supported by increased levels of other CSF biomarkers of immune responses in incident delirium, such as neopterin and astroglia-derived S-100β." (PMID 30390679, 2018).